PDCD1 (programmed cell death 1)
Diseases named in the same sentence as PDCD1 in open-access papers (continued):
Sharing a sentence is not in itself a finding about the gene and the disease.
cancer (continued). "Furthermore, positive correlations of PRC1 and some immune checkpoint genes (CD274, CTLA4, HAVCR2, LAG3, PDCD1, PDCD1LG2, TIGIT, and CD86) were observed in several cancers, especially BLCA, BRCA, KIRC, LUAD, LIHC, PRAD and THCA." (PMID 37563591, 2023). "The results demonstrated that SERPINE1 expression was positively correlated with the expression of most inhibitory immune checkpoints, including CD274 (PD-L1), PDCD1 (PD-1), CTLA4, and HAVCR2 (TIM-3) in most cancers, especially GBM-LGG, KIPAN, UVM, PAAD, and COAD-READ." (PMID 37680718, 2023). "Furthermore, a notable heterogeneity was observed in the relationship between Eph receptors/EFN ligands and main checkpoints (CD274, PDCD1, CTLA4, and LAG3) in different types of cancer." (PMID 37637034, 2023). "Notably, the FCRL family genes demonstrated a significant positive correlation with several immunostimulators, particularly TIGIT, PDCD1, and BTLA, across a range of cancer types." (PMID 37285836, 2023). "Then, a pan-cancer differential expression analysis was performed, and we found that genes such as CXCL13, ITM2A, NR3C1, SRGN, COTL1, and PDCD1 were significantly up-regulated in SC-2 cells compared with other cells in at least five cancer types, but not in SC-10 cells." (PMID 36049666, 2023). "Immune checkpoint inhibitors (ICIs) targeting programmed cell death 1 (PD-1), programmed cell death ligand 1 (PD-L1), or cytotoxic T lymphocyte antigen 4 (CTLA4), has been become one of the most important breakthroughs in cancer therapy." (PMID 37520574, 2023). "An elevated TMB correlated with increased response to immuno-oncological drugs in multiple clinical trials, of which five evaluated the efficacy of a combination of anti-programmed cell death-1 (PD-1)/programmed cell death ligand-1 (PD-L1) and neoadjuvant chemotherapy in TNBC cancer patients." (PMID 36066779, 2022). "Furthermore, CCNA2 is positively associated with expressions of immune checkpoints (CD274, CTLA4, HAVCR2, LAG3, PDCD1, and TIGIT) in most cancer types." (PMID 35480884, 2022). "Though immunotherapy with programmed cell death-1 (PD-1) checkpoint blockade has achieved great progress in many types of cancers, a subset of cancer types still shows less or no response." (PMID 36008936, 2022). "PDCD1, CD274, CTLA4, LAG3, C10orf54, and BTLA expression had positive correlations in most cancer types, and in approximately half of the cancer types, GBP1 expression is positively correlated with CD276 expression." (PMID 35222540, 2022). "When querying the Cancer Genome Atlas data set, we found positive correlations between IL1B expression and infiltration of immunosuppressive PMNs and expression of their chemoattractant, CXCL1, and PDCD1 expressions in patients with KM-LUAD." (PMID 35471938, 2022). "CCNA2 was positively correlated with expressions of CD274, CTLA4, HAVCR2, LAG3, PDCD1, and TIGIT in most cancer types, which indicated the CCNA2 expression may act as a marker after immunotherapy." (PMID 35480884, 2022). "The expression of immune checkpoint (ICP) genes, such as PDCD1 (PD1), CD274 (PDL1), CTLA4, LAG3, and HAVCR2 (TIM3) has been utilized in predicting the response of patients to immune checkpoints therapy in a variety of cancers including PAAD." (PMID 35601487, 2022). "In addition, we studied the relationship between the expression of KCC2 (SLC12A5) and NKCC1 (SLC12A2) in pan-cancer and immune checkpoint genes, including SIGLEC15, IDO1, CD274, HAVCR2, PDCD1, CTLA4, LAG3, and PDCD1LG2." (PMID 35372048, 2022). "Immune checkpoint inhibitors (ICIs), such as programmed cell death 1 (PD-1), programmed cell death ligand 1 (PD-L1), and cytotoxic T lymphocyte antigen 4 (CTLA-4), have indicated remarkable improvement in the prognosis for the treatment of dozens of cancers." (PMID 35320931, 2022). "Besides, our research manifested the correlation of SLC7A11 with 8 IC genes, namely CD274 (also known as PD-L1), HAVCR2, LAG3, SIGLEC15, PDCD1LG2, CTLA4, PDCD1, and TIGIT in 33 cancer types." (PMID 36267158, 2022).
cancer (continued). "Moreover, the link between CTLA4, PDCD1, CD86, CD274, and ISCA1 in various cancer types was measured." (PMID 36072584, 2022). "The role of Pdcd1 in DOX-induced apoptosis in cardiomyocytes and cancer cells was opposing." (PMID 35190965, 2022). "The CAFDL signature was significantly positively associated with TGFB1, CD276, CD40, VEGFA, VEGFB, etc., but showed significantly negative correlation with immune checkpoints (such as CD274, PDCD1, CTLA4, TIGHT, and HAVCR2) and anti-cancer immune regulators (IFNG, IDO1, and GZMA)." (PMID 35967425, 2022). "Furthermore, TOP2A was positively associated with expression of immune checkpoints (CD274, CTLA4, HAVCR2, LAG3, PDCD1 and TIGIT) in most cancer types." (PMID 35778520, 2022). "Several agents targeting Cytotoxic T-Lymphocyte Antigen 4 (CTLA4), programmed cell death-1 (PD-1), and Programmed death-ligand 1 (PD-L1) have been approved by the FDA (Food and Drug Administration) for multiple cancer types, and the indications for utilization is constantly expanding." (PMID 35558065, 2022). "Immune checkpoint inhibitors (ICIs), such as programmed cell death 1 (PD-1), programmed death-ligand 1 (PD-L1), and cytotoxic T-lymphocyte antigen 4 (CTLA-4), have been developed as effective agents in cancer immunotherapy." (PMID 34065315, 2021). "Deletion of exhaustion-specific candidate enhancers of PDCD1 suppress the expression of PD-1 in an in vitro model of T cell dysfunction and in HA-28z CAR T cells, suggesting enhancer editing as a path forward in improving cancer immunotherapy." (PMID 34285077, 2021). "However, CD8 T cells expressed an upregulation of programmed cell death protein 1 (PDCD1 or PD1), a major mechanism contributing to CD8 T cell exhaustion in cancer." (PMID 34503297, 2021). "We further explored the correlation between YTHDC2 and eight immune checkpoint‐related genes and found that YTHDC2 was significantly associated with the expression of SIGLEC15, IDO1, CD274, HAVCR2, PDCD1, CTLA4, LAG3 or PDCD1LG2 in almost all types of cancers except for CESC and TGCT." (PMID 34312987, 2021). "PDCD1, CTLA4, TIM3, TIGIT, and LAG3 play key roles in the immune evasion of cancer cells." (PMID 34844217, 2021). "The advent of immunotherapy—including programmed cell death 1 (PD-1), programmed cell death-ligand 1 (PD-L1), and cytotoxic T-lymphocyte antigen 4 (CTLA-4) immune checkpoint inhibitors—has revolutionized the therapeutic paradigm across a wide range of cancers." (PMID 34944931, 2021). "Moreover, CTLA4, PDCD1 (PD-1), and CD274 (PD-L1), as the primary immune checkpoints in cancers, had the highest expression level in IS2 and the lowest level in IS1 (p < 0.05)." (PMID 34404444, 2021). "Cancer cells evade the host’s immunity by inhibiting immune effector cells, particularly cytotoxic (CD8+) T cells, by employing immune checkpoint pathways, such as programmed cell death-1 (PD-1) and cytotoxic T-lymphocyte antigen-4 (CTLA-4)." (PMID 33931473, 2021). "Immune checkpoint blockade antibodies that augment the effector T cell activity by blocking inhibitory molecules such as programmed cell death 1 (PD-1), its ligand PD-L1 and cytotoxic T-lymphocyte antigen-4 (CTLA-4) have achieved unprecedented advances in numerous cancer types." (PMID 34063752, 2021). "Blocking the immune checkpoints including programmed cell death 1 (PD‐1)/programmed cell death 1 ligand (PD‐L1) and cytotoxic T‐lymphocyte antigen‐4 (CTLA‐4) significantly prolongs the overall survival of 20–30% patients of most subtypes of cancers." (PMID 34293829, 2021). "One example is the programmed cell death-ligand-1 (PD-L1) secreted by cancer cells, which interacts with specific receptor, such as programmed cell death-1 (PD-1), expressed by lymphoid and non-lymphoid immune cells." (PMID 32708484, 2020).
cancer (continued). "As new immunotherapeutic agents are being rapidly adopted in many cancers including NPC, promising response rates to the anti-programmed cell death-1 (PD1)-targeted therapy in the heavily pretreated NPC patients with locally recurrent disease have been demonstrated." (PMID 33255751, 2020). "Although PD-1 has not been studied in MCs, PDCD1 deletion in myeloid cells induces antitumor immunity in a mouse model of cancer." (PMID 32722549, 2020). "Similarly, other immune disorders and cancers may be treated with monoclonal antibodies targeting cancer-specific antigens or immunosuppressive molecules present on immune cells such as cytotoxic T-lymphocyte-associated protein 4 (CTLA-4) and programmed cell death-1 (PD-1)." (PMID 32259744, 2020). "Over the past decade, poly(ADP-ribose) polymerase (PARP) inhibitors (PARPi) and monoclonal antibodies that block immune checkpoints, such as programmed cell-death 1 (PD-1) and cytotoxic T lymphocyte antigen 4 (CTL-4), have transformed the treatment of multiple types of cancers." (PMID 32526888, 2020). "Additional potential gene targets are identified that have more highly correlated expression with CD3E than PDCD1 (ranked #55) and CTLA4 (ranked #103) when we expanded the list of studied genes from our 40-candidate list to all genes known to be expressed in cancer." (PMID 31360302, 2019). "Of these, the average expression of the two genes, including CD70 and PDCD1, and the 12 isoforms derived from the seven genes, including CD40, CD70, IL6, IL10, STAT1, STAT6, and TNFRSF14, were cancer immunotherapy-related genes (false discovery rate (FDR) < 0.01)." (PMID 31292525, 2019). "Immune checkpoint inhibitors, especially programmed cell death 1(PD-1) and programmed cell death-ligand 1(PD-L1) have captured our attention as new therapeutic options for patients with selected advanced cancer for which no effective treatment yet existed." (PMID 29545941, 2018). "PDCD1 expression also revealed a strong activating effect on apoptosis (41%), EMT (22%), hormone AR (12%), hormone ER (28%) and cell cycle (9%) pathways, and a potentially inhibitory effect on hormone AR (6%), hormone ER (9%), RTK (19%) and TSCmTOR (6%) pathways, in pan-cancer." (PMID 40076932, 2025). "Pembrolizumab, an immune checkpoint inhibitor (ICI) that exhibits antitumour effects by inhibiting programmed cell death 1 (PD-1), has been approved for the treatment of malignant melanoma, non-small-cell lung cancer (NSCLC), urothelial carcinoma, renal cell carcinoma, and other types of cancer." (PMID 38365819, 2024). "More importantly, the expression of PIK3R4 in DLBCL was correlated with the immune cell content in the cancer microenvironment, CD8(+) T-cell and neutrophil infiltration and the levels of several immune checkpoint molecules, including BTN3A2, BTN3A1, PRF1, CXCL9, PDCD1, and TIGIT." (PMID 37670973, 2023). "The programmed cell death 1 (PD-1) receptor is found on activated T cells, and its ligand PD-L1, is a major co-inhibitory checkpoint signal used by tumors to block the cytotoxic T lymphocyte (CTL) activity, promote T cell apoptosis, and allow cancer cells to escape immune surveillance." (PMID 37658376, 2023). "Additionally, the combination of IDO1 inhibitors together with immune checkpoint inhibitors, such as anti-programmed cell death 1 (PD1) and anti-programmed cell death ligand 1 (PD-L1), have opened new avenues towards increasing the efficacy of immuno-oncology in cancer treatment." (PMID 36769059, 2023). "We further explored the correlation between the expression of LIPT1 and eight immune checkpoints (PD-L1, CTLA4, HAVCR2, LAG3, PDCD1, PDCD1LG2, SIGLEC15, and TIGIT), and found that LIPT1 levels were correlated with the expressions of these immune checkpoints, especially PD-L1, in most cancer types." (PMID 35837286, 2022).
cancer (continued). "For example, programmed cell death 1 (PD-L1), cytotoxic T lymphocyte antigen 4 (CTLA4), and the indoleamine 2, 3-dioxygenase 1 (IDO1) have achieved impressive success in the treatment of different cancer types, especially the combined treatment of PD-L1 and CTLA4." (PMID 35778697, 2022). "An example of this is seen with PD-L1 (programmed cell death 1) which is occasionally over expressed by tumor cells; upon binding with its cognate receptor PD1 on T cells, pathways such as stemness or chemo-resistance can be activated in cancer cells while suppressing anti-tumor immunity in T cells." (PMID 34512714, 2021). "This difference could explain the starkly different Kaplan–Meier plots that were identified for the PDCD1/CD274-correlated genes, with the majority of cancers showing the same pattern for the co-expressed genes whilst esophageal and renal were notably different." (PMID 34067485, 2021). "Our study of nearly one-thousand patients with fatty liver disease, comparing 391 with cancers to 594 without, indicates that genetic variation in a gene (PDCD1) that codes for the T cell receptor PD-1 may be important." (PMID 33808740, 2021). "In fact, immune checkpoint blockade (ICB) with anti-programmed cell death 1 (anti-PD-1), anti-programmed cell death ligand 1 (anti-PD-L1), and anti-CTLA-4 antibodies have demonstrated their clinical efficacy in treating previously untreatable advanced-stage cancer patients since 2011." (PMID 32231116, 2020). "Immune-checkpoint inhibitors, targeting programmed cell death-1 (PD-1), programmed cell death ligand-1 (PD-L1), or cytotoxic T-lymphocyte protein 4 (CTLA-4), can specifically block the corresponding immunosuppressive signals and exhibit potential efficacy on malignant tumor including advanced HCC." (PMID 33330071, 2020). "The recent development of anti-programmed cell death-1 (PD-1) antibodies, pembrolizumab (Keytruda) and nivolumab (Opdivo), and a pan-tropomyosin receptor kinase (TRK) inhibitor, larotrectinib (LOXO-101), has established a new paradigm in anti-cancer drug development." (PMID 29764494, 2018). "Inhibition of the blocking responses to T cell activation using anti-PDCD1, anti-CTLA4, or anti-CD274 antibodies has proven clinically to result in improved responses for a subset of patients with metastatic melanoma, NSCLC, and potentially other forms of cancer." (PMID 28822103, 2018). "This potential as a therapy was first observed in mice with cancer but no microbiome, as these animals demonstrated a different response when treated with anticancer drugs, including cisplatin, cyclophosphamide, and anti-programmed cell death 1 protein (PD-1) immunotherapy." (PMID 37083032, 2023). "In addition, there is early evidence to show that VOC patterns detected by eNose can also predict response to novel cancer treatments, as demonstrated in patients with advanced non-small cell lung cancer and anti-programmed cell death 1 (anti-PD-1) immunotherapy." (PMID 33321951, 2020). "CTLA4, PDCD1, and LAG3 were significantly up-regulated in 4–5 cancers, while all of them were not dysregulated in PRAD." (PMID 35741849, 2022). "Our analysis of LRRC59 in relation to pan-cancer immune infiltration and immunotherapy reveals a positive correlation between LRRC59 expression and TIM-3 and TIGIT, while a negative correlation with LAG-3 and PDCD1." (PMID 38738999, 2024). "In addition, there was no induction of autophagy in cancer cells (K562 and MCF-7), regardless of Pdcd1 overexpression (data not shown)." (PMID 35190965, 2022). "It was identified that HAVCR2 had positive infiltration scores in all cancer types, whereas a negative infiltration score was noted for CXCL13 (in LGG and DLBCL), LAG3 (in DLBCL and AML), LAYN (in CHOL, KICH, AML, LGG, PCPG, THCA and UCS), PDCD1 (in DLBCL, AML and THYM) and TIGIT (DLBCL and AML)." (PMID 40076932, 2025).
cancer (continued). "Notably, transcripts for PD-1 (Pdcd1) were observed only in T cell clusters whereas PD-L1 (Cd274) transcripts were more abundant in neutrophils, DCs and macrophages and PD-L2 (Pdcd1lg2) in DCs and not in EGFR+ cancer cells." (PMID 35624211, 2022). "Therefore, CXCR4, PDCD1 and MAP1LC3C may function as non-negligible factors in cancer immunity." (PMID 36173625, 2022).
infection (44 papers, 2012 to 2026). The state of being infected such as from the introduction of a foreign agent such as serum, vaccine, antigenic substance or organism. "Comparisons across the early- and late-stages of infection showed that cells from CHs had an early expression of genes associated with exhaustion (PDCD1, ENTPD1), and cytotoxicity, including NK-like genes NKG7, GNLY, KLRC2, and KLRC3 (encoding for NKG2C and NKG2E, respectively)." (PMID 36477661, 2022). "Transcriptomic and protein-level analyses revealed that PDCD1 (encoding PD-1) was significantly upregulated in CD4+ T cells from AG ferrets at baseline and during infection, indicating a pre-existing exhaustion phenotype." (PMID 40794649, 2025). "Knockout of PDCD1 improved the CTL motility at 14 days post infection and enhanced the expression of cytotoxicity markers." (PMID 38742109, 2024). "Eight days after infection, both LCMV strains showed increased expression of genes associated with CD8+ T cell activation, such as Pdcd1, Rgs16 and Lag3, in agreement with previous findings." (PMID 37813964, 2023). "Analysis of Pdcd1 sgRNA-containing P14 CD8+ T cells following LCMV Clone 13 infection revealed significantly reduced PD-1 expression levels, as expected." (PMID 30971695, 2019). "Conditional Pdcd1fl/fl;Mb1-Cre;Pax5+/− mice were generated, where Pdcd1 is deleted upon B-lineage commitment at the pro-B-cell stage, and we examined whether Pdcd1fl/fl;Mb1-Cre;Pax5+/− animals were prone to infection-induced B-ALL." (PMID 41283237, 2025). "Moreover, during acute infection of WT mice 8 dpi, chromatin immunoprecipitation (ChIP) assays show increased Blimp-1 binding to Pdcd1 relative to naive cells at site 2 (between conserved region C [CR-C] and the Pdcd1 transcription start site)." (PMID 39083377, 2024). "Calculating the differentially expressed genes revealed that genes such as Nkg7, Lgals1, Pdcd1, and Ccr2 were significantly upregulated in expanded cells in at least one infection condition and demonstrated consistent trends in expression for all infection groups." (PMID 35185882, 2022). "As an extension of our preceding works, we aimed at performing an immunophenotypic analysis (in terms of memory markers and Programmed cell death 1 (PD-1) expression) of the CD8+ T-cell differentiation profile found in primary infection with viral control and subsequent disease progression." (PMID 25093660, 2014). "It was reported that soluble PD-L1 and soluble PD-L2 could block the cell surface binding of PDCD1 to its functional ligand, thereby up-regulating immune response, increasing T cell proliferation in chronic infection, and participating in the anti-infection process." (PMID 37644514, 2023). "Genes characteristic of T cell exhaustion were upregulated in the chronic LCMV infection (e.g., Pdcd1, Tox, Lag3), whereas genes associated with memory formation and inflationary phenotypes were upregulated in the acute LCMV (e.g., Il7r) and latent MCMV (e.g., Klrg1) infections." (PMID 35185882, 2022). "For example, the PDCD1 exhibited higher chromatin accessibility in the gene region of the elderly group, which might be part of the reason why older individuals were prone to infection." (PMID 32780218, 2020). "During the early stages of infection, we observed increased function in Selplg-/- P14 CD8+ T cells and decreased function in Pdcd1-/- and Selplg-/-Pdcd1-/- P14 CD8+ T cells." (PMID 39912665, 2025). "As expected, comparison of T cells from naive versus LCMV-infected mice revealed the emergence of proliferating T cell clusters marked by Ki67 expression with infection, as well as that of exhausted CD8+ T cells and T helper 1 (TH1)-like CD4+ T cells, marked by high expression of Tox and Pdcd1." (PMID 41094201, 2025).